MAPK7 (mitogen-activated protein kinase 7)
Diseases named in the same sentence as MAPK7 in open-access papers (continued):
Sharing a sentence is not in itself a finding about the gene and the disease.
tumor (161 papers, 2007 to 2026). "MAPK7 loss affects macrophage residency and the lung phenotype of tumour bearing animals despite MAPK7 loss only occurring in tumour cells." (PMID 32655131, 2020). "MAPK7 loss in primary tumours decreases MAPK7 expression in the lungs, suggesting that MAPK7 regulates a positive feedback loop for its own expression between the primary and metastatic site." (PMID 32655131, 2020). "MAPK7 loss in xenograft tumours reduces MMP9 expression in TAMs that have intact MAPK7, further supporting our assertion that MAPK7 signals dictate TAM behaviour and phenotype." (PMID 32655131, 2020). "MAPK7-deficient tumours were grown to the same size as control tumours before being tested for metastatic potential and lung clonogenicity, ensuring we compared ‘like for like’." (PMID 32655131, 2020). "Tumor susceptibility in Atm−/− mice is caused by deficiencies in the DNA damage response; therefore, we investigated the effect of Mapk7 loss on DNA damage signaling." (PMID 27793024, 2016). "We show that loss of Mapk7 in the hematopoietic system of Atm−/− mice increases the DNA damage response in thymocytes and delays death by spontaneous tumor development in Atm−/− mice." (PMID 27793024, 2016). "Moreover, in cell lines derived from these 3MC-induced tumors, abrogation of Mapk7 expression by using specific shRNAs decreased in vitro growth and colony-forming capacity and led to a marked loss of tumor growth in vivo." (PMID 35884568, 2022). "The data describing opposing roles of ATM and MAPK7 in cell cycle regulation and tumor growth suggest that these could be functionally linked." (PMID 27793024, 2016). "On the other hand, ERK5/MAPK7 gene has been found amplified in primary HCC tumors and the MEK5/ERK5 signaling pathway constitutively activated and associated with tumor growth." (PMID 36650140, 2023). "In OS, circ_0001721 functions as a tumor promoter to facilitate malignant tumor behavior by targeting the miR-372-3p/mitogen-activated protein kinase 7 axis (MAPK7)." (PMID 35114890, 2022). "For further analysis, the GlioVis database showed increased mRNA expression levels of CCNB1/CDC42/MAPK7/CD44 oncogenes in GBM tissues compared to non-tumor tissues." (PMID 35008426, 2022). "Herein, we showed that targeting MAPK7 in GBM tumors can potentially improve the strength of TMZ in suppressing tumor cells." (PMID 35008426, 2022). "Strikingly, as revealed by in vivo studies on an orthotopic mouse model, MAPK7 silencing consistently reduced the number of circulating tumor cells and the insurgence of lung metastases." (PMID 35053510, 2022). "We also demonstrate that the classical mitogen-activated protein kinase, ERK5/MAPK7, is required for IL-6 production in tumor cells." (PMID 34671021, 2021). "We have shown in other studies that MAPK7 is a fundamental requirement for a pro-tumour immune contexture." (PMID 32655131, 2020). "Removing the MAPK7/MMP9 signalling axis by RNA interference suppressed tumour burden, metastatic spread and increased overall survival in animals by inhibition of TAM infiltration." (PMID 32655131, 2020). "Here MAPK7 silencing strongly minimises TAM infiltration at the tumour site while increasing the monocyte content." (PMID 32655131, 2020). "Abnormal expression of mitogen-activated protein kinase 7 (MAPK7) has been defined as a biomarker for tumor development in high-grade OS." (PMID 32565738, 2020). "Taken together, this work shows that a tumour-derived MAPK7 signal dictates macrophage behaviour at the primary site plus secondary lesion to provide molecular cues for immune contexture and metastatic spread in PBC." (PMID 32655131, 2020). "Using this approach, we have established the role of a MAPK7/MMP9 signalling axis in recruiting TAMs to PBC tumours to induce lung metastasis." (PMID 32655131, 2020). "RNA interference knockdown of MAPK7 reduces proliferation, colony formation, migration, tumour growth, macrophage residency/polarisation and lung metastasis." (PMID 32655131, 2020).
tumor (continued). "Our results therefore support MAPK7 representing a potentially tractable target for various tumor indications when combined with appropriate therapeutic agents." (PMID 29912950, 2018). "MiR-145 is a well-known tumor suppressor miRNA in CRC targeting the oncogenes ERK5 (mitogen-activated protein kinase 7) and IRS1 (insulin receptor substrate 1); furthermore, its ability to predict survival of CRC patients was also shown." (PMID 29147648, 2017). "It was observed that MAPK7 played a pivotal role in the cell vitality and proliferation of tumor cells." (PMID 29084594, 2017). "The tumorigenicity of MAPK7 has been related to its capacity to interact with promyelocytic leukemia protein and inhibit its tumor suppressor activity." (PMID 27793024, 2016). "Together, these data highlight a broader role for dysregulated MAPK7 in driving tumorigenesis within niche populations of highly prevalent tumor types, and describe current efforts in establishing a robust drug discovery screening cascade." (PMID 26040563, 2015). "Lastly, using reverse-phase protein chip arrays, our work identified potential pharmacodynamic biomarkers of MAPK7 kinase inhibition within MAPK7-amplified tumor cell lines." (PMID 26040563, 2015). "Targeted siRNA knockdown of MAPK7 in two dysregulated cell lines confirmed a driving role for MAPK7 in tumor cell proliferation in vitro." (PMID 26040563, 2015). "MAPK7 was validated as a proliferative oncogenic driver by performing in vitro siRNA knockdown of MAPK7 in tumor cell lines." (PMID 26040563, 2015). "Dysregulated MAPK7 signaling has been demonstrated to play key roles in uncontrolled cell proliferation across several tumor types." (PMID 26040563, 2015). "Using MAPK7 siRNA, we validate a role for dysregulated MAPK7 in driving cell proliferation in established tumor cell lines and describe the development of a cell based ELISA assay to support screening of novel MAPK7 kinase inhibitors." (PMID 26040563, 2015). "b Histogram view of the distribution of MAPK7 IHC scores across the cohort of 74 NSCLC tumor samples." (PMID 26040563, 2015). "Here, we observed that the activated kinase activity of MAPK7 might lead to the recruitment of CD8+ T cells to the tumor microenvironment and might contribute to favorable outcomes in patients receiving anti-PD-1 therapy." (PMID 39039072, 2024). "Furthermore, the presence of MAPK7 gene amplification has been considered as a driver of proliferation in different tumor cell lines." (PMID 35053510, 2022). "Macrophage-rich regions in control primary tumours co-localised with MAPK7 expression." (PMID 32655131, 2020). "Finally, genetic knockdown of MAPK7 combined with the MEK inhibitor cobimetinib in a mutant KRAS NSCLC xenograft model to mediate improved tumor growth inhibition." (PMID 29912950, 2018). "In this sense, MAPK7 has already been studied in OS and might be a promising therapeutic target for this tumor, since modulates growth, proliferation and migration in OS." (PMID 28404946, 2017). "Importantly, by suppressing expression within MAPK7 amplified cell lines, we were able to validate MAPK7 as a driver of tumor cell proliferation and engineer a stable cell line assay for screening of candidate MAPK7 small molecule kinase inhibitors." (PMID 26040563, 2015). "In summary, the work here identifies and validates a novel role for dysregulated MAPK7 as a tumor driver in clinical samples of NSCLC and EC, and outlines aspects of preliminary work in developing a drug discovery programme to identify novel small molecule inhibitors of MAPK7 kinase activity." (PMID 26040563, 2015). "In order to test the hypothesis that dysregulation of MAPK7 signaling could drive tumor cell proliferation, we undertook a number of studies to explore the functional consequences of silencing MAPK7 gene expression in MAPK7 dysregulated tumor cell lines." (PMID 26040563, 2015).
tumor (continued). "While next-generation sequencing analysis revealed that exosomal miR-143 from OS cells is expressed at higher levels in metastatic SAOS2 cells, other studies suggest miR-143 could suppress tumor metastatic potential by targeting mitogen-activated protein kinase 7 (MAPK7)." (PMID 38203737, 2024). "Another study demonstrates, that the knockdown of multiple kinases, like MAPK7 (mitogen-activated protein kinase 7), induces the expression of epithelial markers, inhibits cell migration, and maintains epithelial phenotypes, thereby reducing tumor invasiveness." (PMID 27529216, 2016). "MAPK7 and therefore MMP9 silencing significantly minimised M2 like TAM infiltration at the tumour site, M1 to M2 polarisation and lung colonisation." (PMID 40442778, 2025). "Similarly, a study on a DEN-induced HCC model reported that Kupffer cells (KCs) and monocyte-derived macrophages (Mo-Mφs) presented distinct gene expression profiles, yet no significant alterations in Mapk7 expression were observed in response to tumor-associated inflammation." (PMID 40942182, 2025). "To validate expression levels of the CCNB1/CDC42/MAPK7/CD44 gene signatures in GBM, we explored the HPA database for IHC to compare gene expression levels between GBM tumor tissues and normal samples." (PMID 35008426, 2022). "To assess the impact of MAPK knockdown on tumor growth, we next evaluated the combination of MEK inhibition with MAPK7 knockdown in the NCI-H2122 xenograft model." (PMID 29912950, 2018). "CIRBP has been reported to be involved in multiple tumor progression via the activation of ERK and p38 MAPK7,42,43." (PMID 30315244, 2018). "It was observed that miR-200b was reduced by TGF-β in vitro and in vivo, and downregulated miR-200b significantly increased the expression of its target gene, AP-2α/MAPK7, which promoted the TGF-β level in tumor tissue." (PMID 29084594, 2017). "The administration of miR-200b promoted tumor regression in vivo and abolished the maintenance of TGF-β-related EMT in AP-2α-and MAPK7-dependent manner in CCA." (PMID 29084594, 2017). "Further, the administration of miR-200b induced a remarkably tumor regression in vivo and reduced the effect of TGF-β-related EMT in AP-2α and MAPK7-dependent manner." (PMID 29084594, 2017). "It was observed that the treatment of miR-200b significantly abrogated the AP-2α/MAPK7/TGF-β expression, leading to increased expression of E-cadherin and TTF-1 and decreased expression of fibronectin and α-SMA in tumor tissues." (PMID 29084594, 2017). "‘M2-like’ and MAPK7-expressing TAMs were almost completely absent in the lungs of mice with shMAPK7 tumours." (PMID 32655131, 2020). "In this study, we show that absence of MAPK7 delays death due to spontaneous tumor development in Atm−/− mice." (PMID 27793024, 2016). "The lungs of mice bearing tumours lacking MAPK7 have fewer ‘M2-like’ macrophages." (PMID 32655131, 2020). "It isn’t clear whether the therapeutic index of MEK/MAPK7 inhibitor combination will be similar or different to serial combination inhibition of the Raf/MEK/ERK pathway, which is highly effective at inhibiting tumor cell proliferation, but which is also somewhat toxic." (PMID 29912950, 2018). "In this study, we have demonstrated that the overexpression of MAPK7 in HCCC cells could upregulate the TGF-β expression to re-activate the miR-200b-induced inhibition of EMT and restore the expression of cyclin D1 and Cdk2 to recover cell cycle arrest for the growth of tumor cells." (PMID 29084594, 2017).
infection (14 papers, 2010 to 2024). The state of being infected such as from the introduction of a foreign agent such as serum, vaccine, antigenic substance or organism. "Infection with R. parkeri upregulated of all the MAPK7/TAK1 transcripts except for AmHem-452393 (12-fold downregulated)." (PMID 36845157, 2023). "In addition, the expression of MAPK7 and MAPK9 was significantly upregulated in the resistant grape plant cultivar following P. viticola BS-4-MW infection, but was downregulated in the susceptible cultivar." (PMID 35572700, 2022). "PIN1 and NF- κB mRNA levels were significantly downregulated after the infection, MHC-I, IRF3, and MAPK7 expressions were significantly upregulated following infection, whereas RMBX expression showed almost no variation." (PMID 29062054, 2017).
adenocarcinoma (8 papers, 2013 to 2024). A common cancer characterized by the presence of malignant glandular cells. "In the BNKL reconstructed network there is an indirect inhibition of MAPK7 by GNAQ which is stronger in the case of adenocarcinoma." (PMID 24565081, 2013).
skeletal dysplasia (1 paper, 2020). Any Mendelian diseases that affects growth and development of the skeleton. "Our previous studies have demonstrated that dysfunction of mitogen-activated protein kinase 7 (MAPK7) can cause skeletal dysplasia." (PMID 32944217, 2020).
MAPK7 also shares sentences with these, for which no sentence is quoted: colorectal cancer (20 papers); colon carcinoma (19); leukemia (11); triple-negative breast carcinoma (11); endothelial dysfunction (10); cardiac hypertrophy (9); myeloma (9); bladder cancer (8); breast tumors (8); neuroblastoma (8); acute myeloid leukemia (7); Hyperglycemia (7); cardiomyopathy (6); cardiovascular diseases (6); Obesity (6); pancreatic cancer (6); cervical carcinoma (5); depression (5); diabetic nephropathy (5); diabetic retinopathy (5); oral squamous cell carcinoma (5); osteoporosis (5); pancreatic ductal adenocarcinoma (5); prostate (5); Cerebral ischemia (4); endometrial cancer (4); mesothelioma (4); prostate adenocarcinoma (4); soft tissue sarcoma (4); Anxiety (3).
A further 107 diseases each share a sentence with MAPK7 in 3 papers or fewer.